EPHA2 (EPH receptor A2)
Diseases named in the same sentence as EPHA2 in open-access papers (continued):
Sharing a sentence is not in itself a finding about the gene and the disease.
cataract (continued). "EPHA2 belongs to the tyrosine kinase family of proteins and is an epithelial cell kinase that has been associated with autosomal dominant cataracts and recently it was implicated in age-related cortical cataracts in humans and mice." (PMID 20361013, 2010). "Recently, Shiels and colleagues reported mutations in EPHA2 that are responsible for autosomal dominant cataracts." (PMID 20361013, 2010). "Recently, it was demonstrated that ephrin-A5 acts as a regulator for EPHA2, and loss of ephrin-A5 function can lead to cataracts in mice." (PMID 20361013, 2010). "Here we report for the first time that variations in the gene for Eph-receptor tyrosine kinase-type A2 (EPHA2) on 1p36 are associated with inherited and age-related forms of cataracts in Caucasians." (PMID 19005574, 2008). "While the mechanism for cataracts in humans with EphA2 mutations remain unknown, changes in ion/fluid homeostasis due to disruption of connexins (GJs) or aquaporins (water channels) can lead to nuclear cataracts." (PMID 34899394, 2021). "Differences in estrogen levels between female and male mice likely underlie the protective effect of female gender during early stages of cataract development in Epha2-knockout mice and correlates with reduced susceptibility to age-related cataract in women on hormone replacement therapy." (PMID 34495288, 2021). "2162G > A, rs116506614) in exon 13 of EPHA2 resulting in a conservative substitution of arginine-to-glutamine (p.Arg721Gln or p.R721Q) in the TK domain of EPHA2 that has been associated with age-related cortical cataract in humans." (PMID 34685586, 2021). "The TT genotype of rs7543472 was shown to be associated with ~2× increased risk for cataracts; rs3754334 might be a variant on the EPHA2 gene that is commonly associated with the risk for ARC in different ethnical and geographical populations." (PMID 27681698, 2016). "Thus we conclude that human EPHA2 SAM domain mutations cause cataracts through the reduction of EPHA2 protein levels." (PMID 22570727, 2012). "The cataract mutations reduced the ability of EPHA2 to promote cell migration." (PMID 22570727, 2012). "Consistent with our hypothesis, it has been shown that mutations in the EPHA2 gene within human chromosome 1p36 region lead to cataracts." (PMID 22570727, 2012). "In an Italian cohort, three single nucleotide polymorphisms (SNPs rs3754334, rs7543472 and rs11260867) in the 3′ region of EPHA2 which harbours highly conserved translational control sequences for localised gene expression were found to be associated with cataracts." (PMID 22412971, 2012). "Finally, variations in at least eight genes underlying genetic forms of cataract (EPHA2, GJA8, GALT, SLC16A12, HSF4, GALK1, FTL, and CRYAA), and at least 10 other diverse genes have been associated to varying degrees with age-related cataract." (PMID 21042563, 2010). "In contrast to the heterozygous genotype and dominant phenotype linked with the p.G948W mutation in EPHA2, the SNPs in the EPHA2 region most associated with age-related cataracts displayed the highest odds ratios when homozygous for the risk allele, consistent with recessive effects." (PMID 19005574, 2008). "Mutations in the EPHA2 gene can cause a variety of congenital and age-related cataracts." (PMID 35295853, 2022). "Similarly, one of the reference missense SNVs, rs116506614 (c.2162G>A, p.R721Q), located in the TK domain of EPHA2, that has previously been associated with age-related cortical cataract, was present in a case with cortical cataract and in a control from our cataract case-control panel." (PMID 29267365, 2017). "Therefore, we examined whether EPHA2 polymorphisms were associated with the susceptibility to age-related cataract in a Han Chinese population." (PMID 21686326, 2011). "This downregulation of EphA2 levels alters the downstream MAPK/AKT pathway and affects other extracellular matrix (ECM) and cytoskeletal genes to cause cataracts." (PMID 35295853, 2022).
cataract (continued). "An effect of genetic background on Epha2-related cataract in mice is consistent with differences in incidence, severity, and penetrance of cataract among individuals carrying mutations in the EPHA2 gene." (PMID 34495288, 2021). "On mixed genetic background, both male (n = 12) and female (n = 10) Epha2+/− mice exhibited mild cataract up to 38 weeks of age, thereafter, male mice displayed higher grade cataracts than female mice and significantly higher at 64 weeks of age (P < 0.01)." (PMID 34495288, 2021). "N-cadherin and β-catenin immunolabeling showed disorganized lens fiber cells and disruption of lens architecture in Epha2−/− and Epha2+/− lenses, coinciding with development of severe cataracts." (PMID 34495288, 2021). "On C57BL/6J background, Epha2+/− mice developed moderate cataract at 27 weeks (P < 0.01) and severe cataract by 38 and 45 weeks of age (P < 0.001); however, the mice on mixed background developed only moderately severe cataracts by 64 weeks of age." (PMID 34495288, 2021). "Overall, these experiments showed that Epha2+/− mice also develop age-related cataract and revealed a significant interactive effect of age and Epha2 genotype on cataract development in Epha2-knockout mice on C57BL/6J background." (PMID 34495288, 2021). "This organised structure is lost in knockout EphA2(-/-) mice, which display altered N-cadherin adhesion junctions and disruption of the actin cytoskeleton, leading to lens structure defects and cataracts." (PMID 33671840, 2021). "Epha2+/+ mice on both genetic backgrounds exhibited only mild anesthetic-induced cataract at all time points; although statistically significant (P < 0.001), the difference is unlikely to be biologically relevant." (PMID 34495288, 2021). "It shows that female gender confers some protection and delays the onset, and genetic background has a major effect on rate of progression of Epha2-related cataract in mice." (PMID 34495288, 2021). "Overall, these results indicate that sex has a small effect on rate of progression of Epha2-related cataract and male mice start to develop cataract earlier than female mice." (PMID 34495288, 2021). "Together, these results suggest that Epha2-related cataract develops significantly faster on C57BL/6J than on FVB:C57BL/6J (50:50) mixed background." (PMID 34495288, 2021). "The observed differences in cataract severity between Epha2+/+, Epha2+/−, and Epha2−/− mice persisted up to 45 weeks of age (P < 0.001)." (PMID 34495288, 2021). "In the present study, using an Epha2-knockout mouse model, we investigated the effect of various biological modifiers, Epha2 genotype, age, sex, and genetic background, on Epha2-related cataract development." (PMID 34495288, 2021). "We and others have shown previously that the ligand ephrin-A5 and receptor EphA2 both play critical roles in normal lens function, as both ephrin-A5−/− and EphA2−/− mice develop cataracts." (PMID 23401654, 2013). "EphA2−/− mice develop congenital cataracts in a manner similar to ephrin-A5−/− mice, developing subcapsular vacuoles leading to lens opacity and rupture." (PMID 23401654, 2013). "Ephrin-A5−/− animals have noticeable lens deficits as early as P6 and become opaque by P21, while EphA2−/− animals develop lens deficits at 1 month of age and cataracts by 5 months." (PMID 23401654, 2013). "Ephrin-A5 knockout (-/-) mice often display anterior polar cataracts while EphA2(-/-) lenses show very mild cortical or nuclear cataracts at weaning age." (PMID 22140528, 2011). "The human EPHA2 gene is located on chromosome 1p36, where linkage with autosomal dominant and autosomal recessive cataracts has been reported." (PMID 21686326, 2011). "Thus, it is unlikely that the significant increase in EphA2-pS898 level in lens epithelial cells from 8-month-old ephrin-A5-/- mice activates EMT in anterior epithelial cells to form cataracts." (PMID 39466050, 2024).
cataract (continued). "The mechanisms for these variable cataracts remain unknown, but this new data about the two modes of EphA2 activation in the lens can be useful to inform possible changes due to known mutations." (PMID 39466050, 2024). "Significant differences in lens phenotypes of mouse models with disrupted EphA2 or ephrin-A5 signaling indicate that genetic modifiers likely affect cataract phenotypes and progression, suggesting a possible reason for the variability of human cataracts due to Eph-ephrin dysfunction." (PMID 35295853, 2022). "We investigated whether age, sex, and genetic background, risk factors for age-related cataract, and Epha2 genotype influence Epha2-related cataract development in mice." (PMID 34495288, 2021). "Moreover, it shows the effect of genetic background and sex on progression of Epha2-related cataract." (PMID 34495288, 2021). "In order to determine whether Epha2 heterozygous-null mice develop cataract with increase in age, different groups of 11, 18, 27, 38, 45, and 52 weeks old Epha2 wild-type (Epha2+/+) and Epha2+/− mice on C57BL/6J background were examined for lens opacity." (PMID 34495288, 2021). "In the present study, we tested this hypothesis in Epha2-knockout mice and found that age as a function of Epha2 genotype, genetic background, and sex significantly influence Epha2-related cataract development." (PMID 34495288, 2021). "Hence, we hypothesized that biological factors that increase the risk of age-related cataract, particularly, age, genetic background, and sex, interact with EPHA2 signaling and influence cataract development, leading to cataract with increase in age in Epha2 heterozygous-null mice." (PMID 34495288, 2021). "EPHA2: Concurrently, the first mutations in the human gene for ephrin type-A receptor 2 (EPHA2) on chromosome 1p were found to underlie autosomal dominant cataract and several germline variants (but not somatic variants) were associated with age-related cortical cataract mapped to the ARCC2 locus." (PMID 38927721, 2024). "Future protein modeling work may reveal insights into whether mutations can affect canonical or non-canonical EphA2 phosphorylation, causing cataracts in different regions of the lens." (PMID 39466050, 2024). "Thus, to confirm this finding, in an independent experiment, we determined progression of cataract in cohorts of Epha2+/+, Epha2+/−, and Epha2−/− mice (n ≥ 18 per group) on C57BL/6J background from 11 to 45 weeks of age or until severe cataract developed (grade 4 to 5)." (PMID 34495288, 2021). "Thus, we also tested whether there were any GJ conductance changes in lenses from 12-month-old control, ephrin-A5–/– and EphA2–/– mice to determine whether GJ conductance changes could account for the age-related cataracts in EphA2–/– lenses." (PMID 34899394, 2021). "To test this hypothesis, we generated Epha2-knockout mice on mixed FVB:C57BL/6J (50:50) genetic background and determined cataract development in Epha2+/+ (n = 17), Epha2+/− (n = 22), and Epha2−/− (n = 23) mice from 11 to 64 weeks of age or until severe cataract developed." (PMID 34495288, 2021). "Since aging was the most important risk factor for age-related cataract, age-dependent reduction of EPHA2 protein expression in normal lens and age-dependent deterioration of lens clarity in Epha2 knockout mice suggests an important role of EPHA2 kinase in cataractogenesis during aging." (PMID 19649315, 2009). "Thus, we hypothesized that sex may influence Epha2-related cataract development." (PMID 34495288, 2021). "The proposed p.G948W missense substitution, cosegregating with cataracts in family Mu, was predicted to reside in the cytoplasmic SAM domain of EPHA2." (PMID 19005574, 2008). "Many human cataracts are reported in the lens cortex where there is increased non-canonical EphA2 activation with age." (PMID 39466050, 2024).
cataract (continued). "Recently, however, it has been reported that mice lacking ephrin-A5, a ligand of Epha2, develop cataracts as a result of impaired lens fiber cell adhesion." (PMID 19005574, 2008). "Similarly, Epha2−/− mice on C57BL/6J background developed significantly severe cataract by 18 and 27 weeks of age compared to those on mixed background (P < 0.001) that developed severe cataract much later, by 38 weeks of age." (PMID 34495288, 2021). "A recent report showed that when the exon 5/intron 6 gene-trapping EphA2−/− mice were backcrossed to the C57BL/6J genetic background, the KO lenses developed progressively more severe cortical cataracts, but the opacity did not progress to whole cataracts or lens rupture." (PMID 35295853, 2022). "However, these EphA2 knockout mice were developed using an in-frame translational stop codon at exon 5 under a 129/Sv and C57BL/6 mixed background and did not develop severe cataracts, though small flecklike opacities were observed within the lens nucleus." (PMID 24705208, 2013).
colon carcinoma (26 papers, 2009 to 2025). "In studies on therapeutic possibilities for patients with colon cancer with K-ras mutation, it was also found that the inhibition of EphA2 further reduces invasion and metastasis." (PMID 27110571, 2016). "In GC, ANXA1-derived peptides bind to EphA2 and target EphA2 for degradation, thereby inhibiting mouse gastric and colon cancer cell proliferation." (PMID 40076516, 2025). "When the expression of EphA2 in cells was evaluated, the EphA2 expression of colon cancer cells was greater than that of HUVECs." (PMID 39766211, 2024). "The expression of EphA2 is up-regulated in cervical cancer and colon cancer cells, which is mediated by the metabolic changes (AMP-activated protein kinase (AMPK)–dependent metabolic reprogramming) in tumor cells." (PMID 35603176, 2022). "Again, Ephexin1, EGFR, and EphA2 were at significantly higher levels in lung and colon cancer tissues than in normal lung and colon tissues." (PMID 35668076, 2022). "EPHA2 is aberrantly stabilized in colon cancer cells by a Src-dependent mechanism implicating inactivation of the SLAP-UBE4A ubiquitination complex." (PMID 34999732, 2022). "Fourth, to further validate the inhibition of cell lysis by tumor-reactive Vδ1 T cells, we used EPHA2 knockouts in renal and colon carcinoma cell lines." (PMID 34691070, 2021). "In a comparative study we have shown that EphA2 and EphB4 indeed seem promising targets for image-guided surgery for colon cancer, but with EphB4 having more consistent results." (PMID 32751634, 2020). "Recent studies have indicated that dysregulation of miRNAs results in dysregulated EphA2 in several kinds of solid tumors, including prostate, breast, and colon cancers." (PMID 29273006, 2017). "Since CT26 (colon carcinoma derived) cells endogenously express high levels of both Anks1a and EphA2, we used this cell line for studying the subcellular localization of Anks1a." (PMID 27619642, 2016). "Human EphA2 (hEphA2) is an early detection marker protein for various tumors including lung, breast, and colon cancer." (PMID 26177208, 2015). "When tested on the mouse EphA2-expressing colon cancer cell line MC38-CEA, only IgG28 showed high affinity cross-reactivity to the murine EphA2 receptor Kd = 1 nM and was competitive with the ephrinA1-Fc ligand with an IC50 = 0.89 nM." (PMID 20130824, 2009). "Moreover, EPHA2 phosphorylation on Tyr594 by Src amplifies Akt signaling, leading to colon cancer cell invasion." (PMID 34999732, 2022). "This ability can be reduced by blocking EphA2 in endometrial carcinoma cells or knockout of EPHA2 gene in renal and colon tumor cells, which indicates the interaction of EphA2 and γδ T cells play an important role in enhancing the susceptibility of γδ T cytotoxic reactivity." (PMID 35603176, 2022). "As small intestine and colon tumors are believed to arise from intestinal stem cells, hence the hypothesis that EphA2 could be involved in tumorigenesis." (PMID 32316101, 2020). "Through qRT-PCR testing, we observed that in colon cancer tissue, the mRNA expression levels of VEGFA (p < 0.05), TIMP1 (p < 0.0001), MYC (p < 0.0001), and EPHA2 (p < 0.05) were higher than in normal tissue." (PMID 38773226, 2024). "To validate our data analysis results, we extracted total RNA from patient colon cancer tissue and corresponding normal colon epithelial tissue and measured the mRNA expression levels of TIMP1, VEGFA, MYC, MSLN, EPHA2, ABHD2, and CD24." (PMID 38773226, 2024). "For example, ANKS1A regulates the stability and recycling of EGF receptor, the degradation of EphA8 and EphA2 in mouse embryonic fibroblast, and COPII-mediated anterograde transport of EphA2 and ErbB2 in a colon carcinoma cell line." (PMID 37296980, 2023). "In contrast, agonistic antibodies have been shown not to inhibit the growth of breast and colon tumor xenograft despite strong downmodulation of EphA2 in tumors." (PMID 20130824, 2009).
colon carcinoma (continued). "Phospho-proteomic analyses revealed that, while not impacting on the global tyrosine phospho-proteome in colon cancer cells, this region modulates phosphorylation of specific membrane-localized tyrosine kinases needed for Src oncogenic signaling, including EPHA2 and Fyn." (PMID 34999732, 2022). "EphA2, which is cleaved in the extracellular region by membrane type 1 matrix metalloproteinase (MT1-MMP) and released extracellularly, is not highly enzymatically active; rather, colon cancer expresses high levels of EphA2." (PMID 39766211, 2024).